CACNA1F (calcium voltage-gated channel subunit alpha1 F)
Diseases named in the same sentence as CACNA1F in open-access papers (continued):
Sharing a sentence is not in itself a finding about the gene and the disease.
choroideremia (3 papers, 2020 to 2024). Choroideremia (CHM) is an X-linked chorioretinal dystrophy characterized by progressive degeneration of the choroid, retinal pigment epithelium (RPE) and retina. "This study investigated two novel splice-altering variants, CHM NM_000390.4:c.941-11T>G and CACNA1F NM_005183.4:c.2576+4_2576+5del implicated in choroideremia and cone dystrophy (COD), respectively, resulting in significant visual loss." (PMID 39858572, 2024). "In this study, two novel VUS, CHM c.941-11T>G and CACNA1F c.2576+4_2576+5del, were investigated to assess their splice-altering potential and association with the IRDs choroideremia and cone dystrophy." (PMID 39858572, 2024). "Six cases were classified as “other” phenotypes and included one case each of ocular albinism, CACNA1F associated disorder, and two cases each of Choroideremia and Pseudoxanthoma Elasticum." (PMID 35672425, 2022).
Obesity (3 papers, 2020 to 2021). Accumulation of substantial excess body fat. "CACNA1F (L-type voltage-dependent calcium channel a1F), involved in the differentiation of adipocytes and related to the etiology of obesity, was found to be under selection in the Chinese Debao pony." (PMID 31940795, 2020).
Stickler syndrome (3 papers, 2023 to 2024). Stickler syndrome is an inherited vitreoretinopathy characterized by the association of ocular signs with more or less complete forms of Pierre-Robin sequence, bone disorders, and sensorineural deafness (10% of cases). "Exome sequencing identified 21 potential pathogenic variants of 13 genes in 20 of 75 (26.7%) probands, including genes for Stickler syndrome (COL11A1 and COL2A1; 6/20), FEVR (FZD4, LRP5, and TSPAN12; 5/20), and others (FBN1, GPR179, ZEB2, PAX6, GPR143, OPN1LW, FRMD7, and CACNA1F; 9/20)." (PMID 38243264, 2024).
visual disorders (3 papers, 2015 to 2024). "Based on extremely heterogeneous clinical presentations, CSNB2 manifests as a spectrum of visual disorders that originate from various mutations in CACNA1F." (PMID 39531384, 2024).
autism (2 papers, 2014 to 2020). Persistent deficits in social interaction and communication and interaction as well as a markedly restricted repertoire of activity and interest as well as repetitive patterns of behavior. "However, mutations in CACNA1F have also occurred in idiopathic autism, supporting its role as a risk gene in the condition." (PMID 25477785, 2014). "In support of this, a form of X-linked intellectual disability (XLMR) associated with congenital stationary night blindness, caused by gain-of-function mutations in another L-type voltage-gated calcium channel gene, CACNA1F, also exhibits comorbidity with autism." (PMID 25477785, 2014).
ovarian carcinoma (2 papers, 2020 to 2021). A malignant neoplasm originating from the surface ovarian epithelium. "Moreover, the Spearman correlation was analyzed to see if L- and T-type calcium channel genes (CACNA1D, CACNA1F, and CACNA1H) were correlated with the expression of stem cell markers in the ovarian cancer patients (GSE53963 and GSE14764)." (PMID 32230901, 2020). "Next, we questioned whether the expression of three L- and T-type calcium channel genes (CACNA1D, CACNA1F, and CACNA1H) correlates with the survival of ovarian cancer patients." (PMID 32230901, 2020). "BKCa and calcium channels may be a suitable pharmacological target for treating recurrence and drug resistance in late-stage ovarian cancer patients who exhibit amplification of the KCNMA1 gene and calcium channel subunits genes (CACNA1D, CACNA1F, and CACNA1H)." (PMID 33923707, 2021).
alcohol dependence (1 paper, 2021). Physical and psychological dependence on alcohol. "In particular, Cacna1f (Cav1.4) was negatively correlated with sIPSC frequency (which reflects basal CeA GABA release), supporting its potential role in alcohol dependence." (PMID 34573170, 2021).
anaplastic large cell lymphoma (1 paper, 2022). Anaplastic large cell lymphoma (ALCL) is a rare and aggressive peripheral T-cell non-Hodgkin lymphoma, belonging to the group of CD30-positive lymphoproliferative disorders, which affects lymph nodes and extranodal sites. "On the other hand, downregulation of CACNA1C transcripts (coding for CaV1.2) was seen in centroblastic lymphoma, CACNA1F (coding for CaV1.4) in anaplastic large cell lymphoma, and CACNA1G (coding for CaV3.1) in mantle cell lymphoma." (PMID 36330491, 2022).
autism spectrum disorder (1 paper, 2021). A spectrum of developmental disorders that includes autism, and Asperger syndrome. "Our review has highlighted CACNA1C, CACNA1F, CACNA1I, CACNA2D1 and CACNA2D2 as additional genes for epilepsy, and CACNA2D1 for autism spectrum disorder." (PMID 33985586, 2021).
breast carcinoma (1 paper, 2016). "Of the L-type calcium channel α1 subunits, expression of CACNA1D, CACNA1S, but not CACNA1C, was detected in MDA-MB-231 cells at the mRNA level (CACNA1F was not tested as it appeared to be often downregulated in breast cancer clinical samples)." (PMID 27910855, 2016). "Furthermore, while all four L-type calcium channel α1 subunits are expressed at low levels in both healthy breast and breast carcinoma samples (IST Online), CACNA1D is the most commonly overexpressed α1 subunit in breast carcinoma while CACNA1F is often downregulated." (PMID 27910855, 2016).
depression (1 paper, 2023). "Genes associated with depression or neuro-diseases were found in this study, such as ABCG1, ASMTL, CACNA1F, COX7A1, GRID2, HTR3E, and SHANK2." (PMID 37766304, 2023).
epilepsy (1 paper, 2021). A brain disorder characterized by episodes of abnormally increased neuronal discharge resulting in transient episodes of sensory or motor neurological dysfunction, or psychic dysfunction. "Our review has further revealed variants in CACNA1C, CACNA1F, CACNA1I, CACNA2D1 and CACNA2D2 as additional genes related to epilepsy." (PMID 33985586, 2021).
Optic disc pallor (1 paper, 2021). A pale yellow discoloration of the optic disc (the area of the optic nerve head in the retina). "Hence the findings of GCL-IPL thinning and optic disc pallor observed in the current study may either be due to defective CACNA1F function in the inner retinal layers or perhaps even due to transsynaptic changes hypothesized by some in CSNB." (PMID 33668843, 2021).
Pearson syndrome (1 paper, 2024). Pearson syndrome is characterized by refractory sideroblastic anemia, vacuolization of bone marrow precursors and exocrine pancreatic dysfunction. "Remarkably, half of them (n = 4/8) were genotypically attributed to syndromic IRDs (syndromic: COH1, USH2A, RNU4ATAC; Pearson syndrome; isolated: RPGR, RP2, CACNA1F)." (PMID 39596324, 2024).
testicular teratoma (1 paper, 2015). "Only one study satisfied the selection benchmark with a 1.89-fold change in CACNA1F expression in testicular teratoma, wherein CACNA1F ranked in the top 6% of testicular teratoma gene changes and the p-value was 0.018." (PMID 26147197, 2015).
retinal disorder (9 papers, 2013 to 2026). Any disease or disorder of the retina. "Given that CACNA1F is already associated with retinal disorders in other mammals, including humans, this finding adds to its relevance across species." (PMID 41882631, 2026). "The direct link between pathogenic variants in the CACNA1F gene and retinal disorders provides a clear genetic basis for therapeutic approaches." (PMID 40129245, 2025). "Beyond the three classic phenotypic presentations described, several studies further illustrate the heterogeneity of CACNA1F-related retinal disorders." (PMID 40390739, 2025). "X-linked incomplete congenital stationary night blindness type 2 (CSNB2) is a nonprogressive, inherited retinal disorder caused by variants in CACNA1F, encoding the Cav1.4α1 channel protein." (PMID 36191840, 2022). "Pathogenic alterations of the CACNA1F gene are mostly associated with incomplete X-linked congenital stationary night blindness type 2A (CSNB2A, MIM 300071), a non-progressive retinal disorder." (PMID 24124559, 2013). "Notably, damaging alterations of the CACNA1F gene are mostly associated with incomplete X-linked congenital stationary night blindness type 2A (CSNB2A, MIM 300071), a non-progressive retinal disorder." (PMID 24124559, 2013).
cancer (3 papers, 2015 to 2022). A tumor composed of atypical neoplastic, often pleomorphic cells that invade other tissues. "A larger role in human physiology beyond its function in photoreceptors was suggested for CACNA1F; however, the role of CACNA1F in cancer remains obscure." (PMID 26147197, 2015). "There is limited information on the expression of CaV1.4 (CACNA1F) in cancer." (PMID 27342111, 2016). "A small number of genes specific for cancer at baseline were downregulated in APG-treated cancer patients after 3h and 24h (ACVR2B, CACNA1F, DONSON, PIH1D3, PRDM6)." (PMID 35600369, 2022).
infection (2 papers, 2019 to 2022). The state of being infected such as from the introduction of a foreign agent such as serum, vaccine, antigenic substance or organism. "Specifically, the frequency of CD4 TEff cells was disproportionately increased in Cacna1f–/– mice 4 weeks post-infection and demonstrates that CaV1.4 deficiency leads to a skewed T lymphocyte response." (PMID 31736943, 2019).
tumor (2 papers, 2022). "However, the expression of CACNA1F is very low in both tumor and normal tissues, and the prognostic value of ANO5 in PCa has previously been investigated." (PMID 36246559, 2022). "VCGG channels, including CACNA1C, CACNA1D, CACNA1F, CACNA1E, CACNA1A, CACNA1G, CACNA1I, showed significantly higher expression in KIRC than normal cases, whereas CACNA1S and CACNA1H showed higher expression in normal than tumor cases." (PMID 36588677, 2022).
autosomal recessive disease (1 paper, 2015). Autosomal recessive form of disease. "For icCSNB, mutations in CABP4, a neuronal calcium binding protein in the photoreceptor synaptic terminal, cause autosomal recessive disease, while CACNA1F, encoding the alpha 1f subunit of Cav1.4 calcium channel and localized in the photoreceptor ribbon synapse active zone causes X-linked icCSNB." (PMID 26368928, 2015).
CACNA1F also shares sentences with these, for which no sentence is quoted: Åland Island eye disease (13 papers); retinitis pigmentosa (5); X-linked cone-rod dystrophy 3 (5); Blindness (3); channelopathies (3); cone dystrophy (3); age-related macular degeneration (2); Astigmatism (2); deafness (2); Leber congenital amaurosis (2); ocular albinism (2); Photophobia (2); retinal (2); retinal detachment (2); Strabismus (2); X-linked cone-rod dystrophy (2); albinism (1); arrhythmogenic right ventricular cardiomyopathy (1); Ciliopathies (1); cone-rod dystrophy 3 (1); corneal dystrophy (1); Gyrate atrophy (1); Hyperglycemia (1); Intellectual disability (1); leukemia (1); Macular dystrophy (1); Malignant hyperthermia (1); mantle cell lymphoma (1); Marfan syndrome (1); nicotine addiction (1).
A further 13 diseases each share a sentence with CACNA1F in 1 paper.